RN7SKP192 (RN7SK pseudogene 192)
Gene: Miscellaneous RNA gene on chromosome 11 (59,706,057 to 59,706,383, reverse strand). Ensembl gene ENSG00000223223.
Homologues: Orthologues: chimpanzee 7SK (99% identical), mouse Gm56101 (66% identical). Paralogues in human: RN7SKP176 (70% identical), RN7SKP250 (70% identical), RN7SKP124 (70% identical), RN7SKP203 (70% identical), 7SK (69% identical), RN7SKP211 (69% identical), RN7SKP44 (69% identical), RN7SKP79 (69% identical), RN7SKP9 (69% identical), RN7SKP47 (69% identical), RN7SKP90 (69% identical), RN7SKP180 (68% identical), and 284 more.